PLEKHG5 (pleckstrin homology and RhoGEF domain containing G5)
Description:
Functions as a guanine exchange factor (GEF) for RAB26 and thus regulates autophagy of synaptic vesicles in axon terminal of motoneurons (By similarity). Involved in the control of neuronal cell differentiation. Plays a role in angiogenesis through regulation of endothelial cells chemotaxis. Also affects the migration, adhesion, and matrix/bone degradation in macrophages and osteoclasts.
Synonyms: GEF720; KIAA0720; Syx; Tech; ARHGEF45; CMTRIC; DSMA4; HMNR4
Tractability: Antibody: UniProt places it where antibodies can reach, with medium confidence; its Gene Ontology location is reachable by antibodies, with medium confidence. PROTAC: ubiquitination databases record sites on it.
Gene: Protein-coding gene on chromosome 1 (6,467,122 to 6,520,074, reverse strand). Ensembl gene ENSG00000171680.
Subcellular location: Cytoplasm; Cytoplasm, perinuclear region; Cell membrane; Cell junction; Cell projection, lamellipodium
Subcellular location (Human Protein Atlas): Nucleoplasm
Pathways (Reactome):
Signal Transduction: G alpha (12/13) signalling events; NRAGE signals death through JNK; RHOA GTPase cycle; RND1 GTPase cycle; RND3 GTPase cycle
Gene Ontology:
Molecular function: guanyl-nucleotide exchange factor activity
Biological process: positive regulation of canonical NF-kappaB signal transduction; angiogenesis; endothelial cell chemotaxis; endothelial cell migration; regulation of small GTPase mediated signal transduction
Cellular component: anchoring junction; cell-cell junction; cytoplasm; cytosol; endocytic vesicle; lamellipodium; plasma membrane; perinuclear region of cytoplasm
Genetic constraint (gnomAD): Loss-of-function variants: 52 observed, 92.81 expected, observed/expected ratio (o/e) 0.56, 90% interval 0.45 to 0.71. The upper end of that interval is the gene's LOEUF score, 0.71, which puts it in group 2 of 6, group 1 being the genes least tolerant of losing a copy. Missense variants: 1,203 observed, 1,283.8 expected, observed/expected ratio (o/e) 0.94, 90% interval 0.89 to 0.98. Synonymous variants: 592 observed, 544.61 expected, observed/expected ratio (o/e) 1.09, 90% interval 1.01 to 1.16.
Gene-disease validity (ClinGen):
ClinGen rates the evidence that PLEKHG5 causes each of these diseases.
neuromuscular disease (autosomal recessive): Definitive.
Homologues: Orthologues: chimpanzee PLEKHG5 (99% identical), macaque PLEKHG5 (96% identical), pig PLEKHG5 (90% identical), dog PLEKHG5 (89% identical), mouse Plekhg5 (85% identical), guinea pig PLEKHG5 (85% identical), rat Plekhg5 (85% identical), rabbit PLEKHG5 (75% identical), tropical clawed frog plekhg5 (66% identical), zebrafish plekhg5a (51% identical), zebrafish plekhg5b (51% identical), Caenorhabditis elegans rhgf-2 (24% identical). Paralogues in human: PLEKHG7 (14% identical).
Diseases named in the same sentence as PLEKHG5 in open-access papers:
PLEKHG5 is named in the same sentence as 28 diseases in open-access papers, as found by Europe PMC text mining. Sharing a sentence is not in itself a finding about the gene and the disease. The quoted sentences say what the papers report.
glioma (4 papers, 2020 to 2022). A benign or malignant brain and spinal cord tumor that arises from glial cells (astrocytes, oligodendrocytes, ependymal cells). "Another relevant nuclear biomarker is rho-specific guanine-nucleotide exchange factor, PLEKHG5, as its expression levels were associated with higher glioma grades." (PMID 36425564, 2022). "Increased expression level of PLEKHG5 correlated with poorer prognosis and shorter survival time in all glioma patients, suggesting that this nuclear biomarker can have significant prognostic value." (PMID 36425564, 2022). "The PLEKHG5 (pleckstrin homology and RhoGEF domain containing G5) gene encodes a protein that activates the nuclear factor kappa B (NFKB1) signaling pathway and is a novel prognostic biomarker in glioma patients." (PMID 35295987, 2022). "For example, PLEKHG5 is a novel prognostic biomarker in glioma patients and could promote glioma migration and invasion." (PMID 33772655, 2021). "This study provides new insights in the PLEKHG5/RAB26 signalling within U251-MG cells, which suggests potential therapeutic strategies in other glioma cells and further in primary GBM." (PMID 33318498, 2020).
Charcot-Marie-Tooth disease (3 papers, 2013 to 2025). An inherited degenerative disorder involving the peripheral nerves. "Four genes were identified with alterations in more than one family include PLEKHG5, a gene that causes Charcot-Marie-Tooth disease and THBS2, which promotes synaptogenesis." (PMID 29177109, 2017). "Finally, mutations in the PLEKHG5 gene have been associated with various neuromuscular diseases such as Charcot-Marie-Tooth disease and lower motor neuron diseases." (PMID 41234028, 2025). "However, there has been no report of a PLEKHG5 mutation relevant to Charcot-Marie-Tooth disease (CMT), which is also called hereditary motor and sensory neuropathy (HMSN)." (PMID 23844677, 2013). "However, the PLEKHG5 mutation has not been described to cause Charcot-Marie-Tooth disease (CMT)." (PMID 23844677, 2013).
amyotrophic lateral sclerosis (2 papers, 2020 to 2025). Amyotrophic lateral sclerosis (ALS) is a neurodegenerative disease characterized by progressive muscular paralysis reflecting degeneration of motor neurons in the primary motor cortex, corticospinal tracts, brainstem and spinal cord. "Our data highlight the essential role of Atg9 in presynaptic autophagy and suggest that boosting autophagy by physical exercise provides a tool to maintain presynaptic function at the early but not late stages of Plekhg5-associated MND and possibly amyotrophic lateral sclerosis." (PMID 41398973, 2025).
distal hereditary motor neuropathy (2 papers, 2024 to 2025). "More recently, additional PLEKHG5 mutations were frequently identified in patients suffering from autosomal recessive intermediate Charcot-Marie-Tooth disease, distal spinal muscular atrophy, and distal hereditary motor neuropathy." (PMID 41398973, 2025).
glioblastoma (2 papers, 2020 to 2021). The most malignant astrocytic tumor (WHO grade IV). "We have previously shown that the guanine exchange factor (GEF) pleckstrin homology and RhoGEF domain containing G5 (PLEKHG5) plays an essential role in the formation of autolysosomes in glioblastoma cells and induces the transcription factor NF-κB." (PMID 33800955, 2021). "We generated a CRISPR/Cas9-mediated knockout of PLEKHG5 in U251-MG glioblastoma cells and analysed resulting changes." (PMID 33318498, 2020). "Recently, Pleckstrin homology containing family member 5 (PLEKHG5) has been described as a prognostic biomarker in glioblastoma patients." (PMID 33318498, 2020). "In order to study the role of PLEKHG5 in more detail, we developed a model for PLEKHG5 function in the glioblastoma cell line U251-MG." (PMID 33318498, 2020). "Here, we used the CRISPR/Cas9-system for the generation of a PLEKHG5 knockout in human glioblastoma U251-MG cells." (PMID 33318498, 2020). "In summary, a successful knockout of PLEKHG5 could be generated in U251-MG glioblastoma cells." (PMID 33318498, 2020). "PLEKHG5 was reported in glioblastoma multiforme (GBM) and correlates with patient survival." (PMID 33318498, 2020). "We provide substantial evidence that the PLEKHG5/RAB26 pathway is involved in the regulation of autophagy, cell proliferation, cellular morphology, apoptosis and even MGMT expression as well as promoter regulation at least in the U251-MG glioblastoma model system under investigation." (PMID 33318498, 2020). "Although the specific role of LAMP-1 in glioblastoma remains unknown, our results suggest a negative impact of PLEKHG5 depletion followed specifically by a decreased LAMP-1 expression and impaired autolysosome formation on tumour cell survival." (PMID 33318498, 2020).
motor neuron disease (2 papers, 2021 to 2026). "Collectively, these observations reinforce the pleiotropic nature of PLEKHG5, in which clinical expression extends across a continuum from pure motor neuron disease to classical sensorimotor CMT." (PMID 41562385, 2026). "Motorneurons from transgenic mice lacking the GEF Plekhg5 and in which Rab26 activation is deficient show accumulation of SV proteins and enlarged SVs that result in motorneuron disease, indicating that both Rab26 and Plekhg5 participate in the autophagy-dependent degradation of SVs." (PMID 33340068, 2021).
neuropathies (2 papers, 2025 to 2026). "NGS neuropathy panel identified a homozygous PLEKHG5 variant, NM_014799.4:c.59G>A (p.Arg20Gln), classified as a variant of uncertain significance (VUS) by ACMG criteria." (PMID 41562385, 2026). "In conclusion, this case broadens the geographic range of PLEKHG5‐associated neuropathies and underscores the need for systematic genetic testing in atypical neuropathies." (PMID 41562385, 2026). "Collectively, these observations position PLEKHG5‐related neuropathies as part of a pleiotropic spectrum, in which the main discriminators are the distribution and severity of weakness and the presence or absence of sensory involvement." (PMID 41562385, 2026).
Anxiety (1 paper, 2017). Intense feelings of nervousness, tension, or panic often arise in response to interpersonal stresses. "Plekhg5-deficient mice performed similarly in the open field test indicating that anxiety-related behavior is not altered." (PMID 29084947, 2017).
liver cancer (1 paper, 2023). An epithelial or non-epithelial malignant neoplasm that arises from the liver. "In The Human Protein Atlas database, IHC showed that PLEKHG5 protein levels are higher in liver cancer tissues than in corresponding nontumor tissues." (PMID 37248230, 2023).
neuroblastoma (1 paper, 2022). Neuroblastoma (NB) is the most common solid, extracranial childhood tumor. "PLEKHG5 is located in cytoband 1p36.31 which is frequently deleted in neuroblastoma." (PMID 35246212, 2022).
sarcoma (1 paper, 2019). A usually aggressive malignant neoplasm of the soft tissue or bone. "We found that the sarcoma-iPSC MEFs harbor genetic aberrations, including a part of chromosomal abnormalities and mutations at Plekhg5 and Alk, which are identical to those in the secondary sarcomas." (PMID 31488818, 2019).
tumor (7 papers, 2020 to 2025). "Both PLEKHG5 and APOBEC1 were previously suggested as valuable prognostic biomarkers and potential anti‐tumor targets for different cancers." (PMID 40045917, 2025). "KALRN, MCF2/Dbl, NGEF/EPHEXIN, ARHGEF7/βPix/COOL-1, CDC42EP2, DOCK9, NET1, TIAM2, ABR, PLEKHG5, RhoBTB2 and PREX1 were identified as being increased at the tumour rim." (PMID 33256106, 2020). "Furthermore, we detected PLEKHG5 protein levels in 32 HCC patients by western blotting and found that approximately 65% of sample pairs showed significantly increased PLEKHG5 expression in tumor tissues compared with paired normal tissues, while PLEKHG5 was undetectable in most of the other samples." (PMID 37248230, 2023).
cancer (5 papers, 2020 to 2025). A tumor composed of atypical neoplastic, often pleomorphic cells that invade other tissues. "Moreover, these two SBS subtypes differed in somatic mutations in several cancer driver genes, including higher mutation frequency of ERBB2, GATA3 and FGFR4, and lower frequency of DMD, INHBA, OGDHL, PLEKHG5 and RYR2 in subtype 3 than in subtype 1 (P < 0.05)." (PMID 40858906, 2025). "PLEKHG5 is a guanine exchange factor (GEF), which is highly expressed in endothelial cells of the nervous system and in different cancer cells." (PMID 33318498, 2020).
neuromuscular disease (1 paper, 2025). "Although PLEKHG5 has not been directly linked to eclampsia, its role in neuromuscular diseases points out the importance of further research in this area." (PMID 41234028, 2025).
PLEKHG5 also shares sentences with these, for which no sentence is quoted: autism (1 paper); cardiomyopathy (1); diabetic retinopathy (1); endometrial tumors (1); esophageal adenocarcinoma (1); hepatocellular carcinoma (1); hereditary motor and sensory neuropathy (1); lung carcinoma (1); neurodegenerative disease (1); pituitary adenomas (1); post-traumatic stress disorder (1); Retinopathy (1); Sensory neuropathy (1); spinal muscular atrophy (1).